FOXA1 (forkhead box A1)
Diseases named in the same sentence as FOXA1 in open-access papers (continued):
Sharing a sentence is not in itself a finding about the gene and the disease.
tumor (continued). "In tumor cells with loss-of-function mutations of FOXA1 that preserve the ability to form homodimers, concomitant induction of both wild-type and mutant alleles will presumably result in a dominant negative effect of the mutant protein on the regulation of DIV elements." (PMID 39633177, 2025). "Utilizing a larger cohort of 175 NPC and 61 non-cancerous nasopharyngeal epithelia cases, we demonstrated that loss of FOXA1 was significantly associated with larger tumor size, lymphatic metastasis, distant metastasis, advanced clinical stages, and the undifferentiated histological subtype." (PMID 40623983, 2025). "In summary, these results indicate that the loss of FOXA1-SEs may affect the levels of redox metabolites and participate in the regulation of tumor metabolism." (PMID 41330917, 2025). "However, molecular mechanisms by which FOXA1 variants mediate these tumor-promoting activities remain poorly understood." (PMID 38528115, 2024). "In contrast, FOXA1 enrichment clearly distinguished Group-P from the other two groups, highlighting FOXA1’s importance as a TF associated with receptor-positive tumor lineages." (PMID 38429368, 2024). "Loss of FOXA1 significantly decreased the tumor cell proliferation in MCF-7." (PMID 39000600, 2024). "Similarly, mutations in the FOXA1 gene activate AR signaling, promotes tumor growth, facilitating the epithelial-mesenchymal transition, and increasing tumor metastasis potential by inducing transcriptional changes that activate the WNT signaling pathway." (PMID 39296545, 2024). "GATA3-/FOXA1- is linked to tumor extensive necrosis and poor prognosis in UTUC and may serve as a potential biomarker for UTUC patients." (PMID 38425344, 2024). "Interestingly, we found with the RUV-III normalized data that higher expression of the FOXA1 gene is associated with poorer outcome in the luminal B subtype, a conclusion that was obscured by the variation in tumor purity of the TCGA RNA-seq data." (PMID 36109686, 2023). "Our analysis revealed the presence of certain variants within the class‐1 variants, such as F266 and F254, which have been previously associated with promoting tumor growth based on seminal research may explain the higher incidence of FOXA1 mutations in mCRPC." (PMID 37584393, 2023). "Moreover, transduction of FOXA1 in an immortalized prostate epithelial cell line redirected the AR from binding at normal tissue-associated AR binding sites to instead occupy tumor-associated AR binding sites." (PMID 36212399, 2022). "Interestingly, mutations in FOXA1 were predicted to be either gain or loss of function, indicating that FOXA1 can act as an oncogene or tumor suppressor in PCa." (PMID 36139541, 2022). "Thus, one of the genes upregulated by FOXA1, IL-8, promotes tumor survival, metastasis, and is associated with resistance to ER inhibitors." (PMID 33417085, 2021). "By using sequential in vivo recombination, they showed that FOXA1/2 loss in established KRAS-driven neoplasia originating from SPC+ alveolar cells was capable of promoting keratinizing squamous cell carcinomas, illustrating the capacity of these transcription factors to cause transdifferentiation." (PMID 32747478, 2020). "Moreover, concomitant loss of NKX2-1 and FoxA1/2 activity at tumor initiation leads to a distinct differentiation state characterized by expression of multiple markers of the transitional epithelium normally found at the SCJ of the GI tract." (PMID 30475207, 2018). "Context also appears to be critical for the effect of FoxA1/2 loss on tumor growth." (PMID 30475207, 2018).
tumor (continued). "Univariate analysis showed a significant association between RFS and tumour size (p < 0.001), nodal involvement (p < 0.001), adjuvant chemotherapy (p = 0.005), AR status (p = 0.034), AR/FOXA1 co-expression (p = 0.020), TILs density (p = 0.002) and PD-L1 expression by TILs (p = 0.018)." (PMID 29880907, 2018). "FOXA1 mutationstend to occur in the DNA-binding domain, and preliminary data from prostate cancer suggest that mutations inFOXA1 decrease AR signalling and increase tumour growth." (PMID 26884552, 2016). "GATA3 levels were elevated in both the early neoplasias and cancers in this study and were highly correlated with ER and FOXA1 expression, but mutation status in these samples is unknown." (PMID 24887547, 2014). "Mipol1, Foxa1, and Mis18bp1 are three genes associated with cell growth and tumor development." (PMID 23463770, 2013). "Association of FOXA1 Staining with gender, tumor stage, grade, and nodal status." (PMID 22590586, 2012). "In this scenario, orthotopic transplants in syngeneic wild type adult mice of mPrOs carrying tumor-associated Foxa1 mutations will provide a valuable preclinical platform to test the efficacy of RA signaling in counteracting the tumorigenic process according to the specific class of Foxa1 mutations." (PMID 39633177, 2025). "We hypothesized that the correlation between NIS expression and the degree of response to chemotherapy could be explained by the presence of driver or amplifying mutations in the FOXA1 gene, the activity of which is characterized by the formation of a chemoresistant tumor phenotype." (PMID 41283251, 2025). "In this study, FOXA1 index ≥1% was also associated with a longer disease-free interval, overall survival, and cancer-specific survival, by multivariate survival analyses, again with components of clinical stage as covariates of the models (tumor size, nodal status, distant metastasis)." (PMID 31888566, 2019). "Interestingly, the effects of recombinant CCN2 peptide on U-CH1 cells were more pronounced under normoxia than hypoxia, promoting increased expression of CCN1, CCN2, CCN3 and CCN5, the notochord-associated markers SOX5, SOX6, T, CD24, and FOXA1 as well as increased tumour-sphere formation." (PMID 25541962, 2014). "IHC analysis revealed significant differences in FOXA1 expression among normal, benign, and malignant tissues, with levels correlating with tumor stage." (PMID 41683623, 2026). "IHC (immunohistochemistry) staining was performed to assess FOXA1 expression and its correlation with tumor stage." (PMID 41683623, 2026). "NSD2 and its H3K36 methyltransferase activity recruit AR to tumor-specific enhancers, where it cooperates with pioneer factors such as FOXA1, HOXB13, and ETS, redistributing AR binding and amplifying oncogenic signaling." (PMID 41601922, 2026). "Stabilized FOXA1 promotes expression of cell-cycle genes and proliferation, and dual inhibition of EZH2 and USP7 markedly suppresses tumor growth in FOXA1-high PCs in vitro and in vivo." (PMID 41601922, 2026). "Through LASSO-Cox regression and stepwise selection, we constructed a four-gene Tumor-Progressing Fibroblast Riskscore model comprising FOXA1, TBX3, LRIG1, and RNF11." (PMID 41624768, 2026). "In late-stage disease, FOXA1 can “reprogram” AR activity, thereby promoting tumor progression, lineage plasticity, and therapy resistance." (PMID 39745364, 2025). "Its downregulation in NPC, as observed in studies, suggests a tumor-suppressive function, with restoration of FOXA1 in NPC cells leading to a suppression of proliferation and invasiveness." (PMID 40623983, 2025). "FOXA1 plays a key role in PCa and can also be used to determine distinctive phenotypes in this tumor." (PMID 41009328, 2025). "To date, our data suggest that HNF4G is the primary driver of tumor growth, whereas FOXA1 becomes the driver of metastasis, and together, they both contribute to tumor progression and overall survival." (PMID 41168397, 2025).
tumor (continued). "Overall survival is influenced by HNF4G and FOXA1 activity in primary tumor growth and in metastasis, respectively." (PMID 41168397, 2025). "In NPC cells and corresponding xenografts, assays indicated that FOXA1 functions as a tumor suppressor, with its knockdown promoting malignant behaviors such as increased cell proliferation, migration, and invasion." (PMID 40623983, 2025). "To understand how a functional switch occurs from HNF4G-dependent state to a FOXA1-mediated metastatic state in the transition from primary tumor growth to metastatic progression, we explored our engineered human cancer cell line xenograft models." (PMID 41168397, 2025). "Genetic depletion or pharmacological inhibition of HIF1α and PHD1/3 disrupts FOXA1 stability and impairs tumor cell growth and motility, highlighting the therapeutic potential of targeting this axis." (PMID 40643528, 2025). "Examination of tumor growth revealed that knockdown of FOXA1 significantly inhibited tumor growth in mice." (PMID 39789998, 2025). "Overall, the luminal-associated transcriptional programs (FOXA1-EHF-ITGB4) and its downstream ECM-receptor interaction pathway (SPP1, CD44, ITGB4) play a crucial role in IMA, influencing its immunity and tumor risk." (PMID 39584073, 2025). "WT1 and FOXA1 silencing impaired the tumor-sphere forming ability of neurospheres treated with TMZ, decreased the spheroid frequency and reduced the mRNA expression of the stem markers NANOG, OCT4 and SOX2 (Fig. 4Gleft and right panels)." (PMID 40399259, 2025). "Evidence of FOXA1 involvement in tumor progression on the (epi)genetic, transcriptomic, and proteomic levels warrants further investigation of FOXA1 as clinical biomarker and its clinical utility for DCIS risk stratification." (PMID 39723668, 2025). "Frequently mutated in prostate, breast, bladder, and salivary gland tumors, FOXA1 is known to reprogram AR-binding landscapes and influence tumor phenotypes." (PMID 40643528, 2025). "In OC, members such as FOXA1, FOXM1, FOXP4, FOXQ1, and FOXR2 primarily exhibit oncogenic functions, whereas others like FOXO and FOXP1 are associated with tumor-suppressive effects." (PMID 40746724, 2025). "Regarding other tumor-related biomarkers, PAM50 basal BC and downregulation of FOXA1, PR, and ER genes were associated with pCR in the GIADA trial." (PMID 40941037, 2025). "This research not only supports the notion of FOXA1 as a tumor suppressor, in line with previous studies, but also underscores its critical role in tumor progression." (PMID 40623983, 2025). "The data above indicate that reduced FOXA1 expression is significantly associated with aggressive NPC traits, suggesting a role in tumor progression." (PMID 40623983, 2025). "In summary, our study uncovers a pivotal role of CDK12-mediated phosphorylation in enhancing FOXA1’s transcriptional activity and tumor-promoting functions, thereby driving PCa progression." (PMID 41395253, 2025). "Based on expression levels of Ar and Foxa1, we labeled the two tumor-specific epithelial clusters as luminal high (cluster 3) and low (cluster 2)." (PMID 40570057, 2025). "While this manuscript focuses on the regulation and upstream factors of RBM47, future studies should identify pathways and targets downstream of RBM47 that mediate tumor suppression by the FOXA1/RBM47 axes." (PMID 41335176, 2025). "To clarify the role of S1PR1 and FOXA1 in tumor growth, we established an in vivo subcutaneous xenograft model." (PMID 39551792, 2024).
tumor (continued). "This study concluded that basal tumours with KRT5/6, p63, and KRT14 expression had a better response to chemotherapy, while luminal tumours with active PPAR expression and activating mutations in FGFR3 showed expression of KRT20, FOXA1, and GATA3." (PMID 39594166, 2024). "HOXB13 and FOXA1 are enriched at tumor-promoting genes and can open the chromatin to generate a permissive chromatin landscape to support AR activities in androgen-dependent and independent states." (PMID 38201640, 2024). "In endocrine-resistant breast cancer, FOXA1 is significantly amplified and enhances tumour aggressiveness by activating IL-8 signalling to further promote tumour invasion, metastasis and therapy resistance." (PMID 39282472, 2024). "Conversely, FOXA1 shows low expression and exhibits tumor-suppressive effects in pancreatic cancer and nasopharyngeal cancer by inhibiting proliferation and EMT." (PMID 38886389, 2024). "Taken together, these findings suggest that FOXA1 plays a critical role in tumor proliferation in Group-P cells." (PMID 38429368, 2024). "Further in vitro evaluation of predicted interactions between miR-200a-3p and FOXA1 (Forkhead Box A1) confirmed that the tumor-suppressive effects of miR-200p-3a are mediated through negative regulation of FOXA1." (PMID 38785786, 2024). "Established early oncogenic driver alterations including ERG gene fusions as well as FOXA1, CDK12, and SPOP mutations were typically present in both the primary tumor and LN metastatic foci." (PMID 38773085, 2024). "miRNA-21, which is downregulated in most HCC tissues, inhibits tumor growth in human HCC by targeting FOXA1 and induces apoptosis in HCC cells." (PMID 38605023, 2024). "In these cancers, DSCAM‐AS1 modulates the expression of FOXA1 and ERα by interacting with YBX1, influencing YBX1 recruitment to the promoter regions of FOXA1 and Erα and thereby promoting tumour progression." (PMID 39690143, 2024). "Luminal tumours were identified as KRT20+/GATA3+/FOXA1+ and basal tumours as KRT5/6+/KRT14+/GATA3−/FOXA1−." (PMID 39594166, 2024). "Strikingly, motif analysis of the AR cistromes generated from patient specimens revealed the FOXA1:AR half-motif to be exclusively detected in the tumor-specific AR enhancer circuitries, with such chimeric motifs being essentially absent at normal AR sites." (PMID 39251788, 2024). "FOXA1, a member of the FoxA family, is frequently studied in tumor research due to its mediation of histone H1 and DNA genome demethylation, resulting in chromatin relaxation in densely stained regions." (PMID 39440051, 2024). "To better understand if the tumor-level correlation between class-1 FOXA1 alterations and SEMA3C expression is retained in in vitro systems, we first leveraged existing ChIP-Seq datasets from multiple recently-published reports." (PMID 38528115, 2024). "As a tumor suppressor, FOXA1 targets PIK3R1 and inhibits the PI3K/Akt signaling pathway, which plays an inhibitory role in the proliferation, migration, and invasion of male HCC patients." (PMID 38605023, 2024). "They found that high KRT14 and low FOXA1 were expressed in basal subtypes, while luminal tumours had low KRT14 and high FOXA1, categorising micropapillary, nested, and plasmacytoid carcinoma as luminal." (PMID 39594166, 2024). "NSD2-dependent AR sites distinctively harbor the chimeric FOXA1:AR half-motif, which exclusively comprise tumor-specific AR enhancer circuitries defined from patient specimens." (PMID 39251788, 2024). "In the GEPIA database, FOXA1 is significantly overexpressed in BC tumor tissues, and the FOXA1 protein level in BC tumor sample tissues in the HPA database is also significantly higher than that in normal tissues." (PMID 39440050, 2024).
tumor (continued). "They found that organoids expressing the FOXA1 SY242CS mutation formed larger organoids compared to WT FOXA1, suggesting that SY242CS promotes tumor cell growth." (PMID 39253075, 2024). "One of the differentially expressed genes expressed at a higher level in the CCNE1/CDK2-high tumours was FOXA1 (FDR-p value < 0.05; log2 fold changes of 2.2 and 1.1, respectively)." (PMID 38612869, 2024). "It is worth mentioning that in renal tumors, including KIRP, KKIPAN, and KICH, the expression level of FOXA1 in advanced tumor stages III and IV is significantly higher than that in early tumor stages I and II." (PMID 39440050, 2024). "To examine the prognostic significance of FOXA1 expression in NSCLC, we evaluated the correlation between tumor FOXA1 expression levels and patient survival using Kaplan-Meier analysis and the log-rank test." (PMID 39440051, 2024). "When PCa is in a hypoxic tumor microenvironment, both FOXA1 and FOXA2 regulate the hypoxic transcriptional program by binding to HIF1A." (PMID 38605023, 2024). "The miR-18a/low tumours had higher expression of the luminality-associated genes like ESR1, GATA3, FOXA1, XBP1 and TFF1 and a lower expression of the basality-associated genes such as KRT18, KRT17, FOXC1, ANLN, STIL and MIA (p < 0.05)." (PMID 38786043, 2024). "Tumor-immune phenotypes related to FOXA1 were studied by focusing on six immune-related pathways, including CD28 co-stimulation, IL2 signaling, cell recruitment, cytokine–cytokine receptor interaction, interferon signaling, and IL12 signaling." (PMID 37958805, 2023). "Recent work identifying somatic alterations in FOXA1 in cancer have further revealed the myriad of functions this pioneer factor can play in promoting tumor growth." (PMID 37691854, 2023). "Using rapid immunoprecipitation and mass spectrometry of endogenous protein, we identified chromatin-localized interactions between FOXA1 and glucocorticoid receptor (GR) in these tumor cells." (PMID 37691854, 2023). "The median (P25, P75) of FOXA1 H-scores in tumor tissues [277.5 (255.0, 285.0)] was also significantly higher than that in adjacent tissues [90.0 (40.0, 180.0)] (P < 0.001)." (PMID 37568077, 2023). "In our study, the expression levels of AGR2 and FOXA1 in tumor tissues were significantly higher than that in adjacent tissues and there was a positive correlation between them." (PMID 37568077, 2023). "On the one hand, elevated expression of FOXM1 promotes tumour cell proliferation and, on the other hand, FOXA1 inhibits tumour progression by suppression of PIK3R1 expression." (PMID 36688815, 2023). "Luminal tumours, accounting for about 50% of MIBCs, present high expression of urothelial differentiation markers (GATA3, FOXA1, KRT20, uroplakins) and are enriched in activating mutations of FGFR3." (PMID 36944729, 2023). "In CRPC, nuclear localization and overexpression of FOXA1 enhanced tumor growth and metastases by prompting cell cycle progression, whereas decreased luminal FOXA1 is associated with the promotion of NEPC." (PMID 37491794, 2023). "This distinct pattern of co-occurring motifs between ts- and cts-hypoDMRs in EAC is noteworthy, considering that AP-1 family transcription factors contribute to EAC tumor development while FOXA1/2 are required for normal gastrointestinal cell development." (PMID 37620896, 2023). "There was also significant positive correlation between the expression levels of AGR2 and FOXA1 in both tumor tissues (r = 0.441, P < 0.001) and adjacent tissues (r = 0.567, P < 0.001)." (PMID 37568077, 2023). "In contrast, compounds that can inhibit both ligand-dependent and ligand-independent functions of GR, such as ORIC-101, suppress the expression of FOXA1/GR targets below baseline levels, and inhibit proliferation and tumor growth in a dose-dependent manner." (PMID 37691854, 2023).